CFTR (CF transmembrane conductance regulator)
Diseases named in the same sentence as CFTR in open-access papers (continued):
Sharing a sentence is not in itself a finding about the gene and the disease.
lung disease (282 papers, 2004 to 2026). "This suggests that CFTR deficiency contributes to osteopenia independently of nutritional status or pulmonary disease severity." (PMID 40869482, 2025). "The importance of the small airways in the pathophysiology of lung disease in CF is well known, because CFTR dysfunction causes viscous secretions and failure of mucociliary clearance due to respiratory mucin adherence to the airway epithelium." (PMID 40531731, 2025). "In the same year, Laselva and colleagues investigated the impact of Trikafta on two rare CFTR mutations, H609R and I1023_V1024del, both associated with severe lung disease." (PMID 39996840, 2025). "It is mainly characterized by pulmonary disorders and is due to a large panel of mutations in the Cystic Fibrosis Transmembrane Conductance Regulator (CFTR) gene affecting the CFTR protein synthesis and activity." (PMID 38247876, 2024). "In CF, the introduction of CFTR modulator therapy, which targets the basic defect by restoring function of the defective CFTR protein at the apical cell membrane, has immensely improved CF lung disease for those with eligible CFTR mutations." (PMID 39293854, 2024). "The poor correlation between the severity of the CFTR variants and the severity of the lung disease supports the notion that other cofactors contribute to the modulation of the phenotypic expression of the primary genotype." (PMID 38610815, 2024). "Fourteen PwCF carrying F508del-CFTR on at least one allele with advanced lung disease were included." (PMID 36986509, 2023). "As CFTR is expressed in a wide range of organs throughout the body, CFTR dysfunction causes multi-organ disease, including lung disease, pancreatic insufficiency, intestinal obstruction, biliary cirrhosis and bilateral absence of the vas deferens." (PMID 37137509, 2023). "The severity of lung disease and the rate of lung function decline are highly variable across CF patients, and cannot be fully explained by variations in CFTR alleles or other modifier genes." (PMID 37052589, 2023). "Chronic bacterial infections are a hallmark of ion channelopathies that cause lung disease, such as CF, thus the impact of CFTR dysfunction in IAV-infected HBECs on the development of bacterial infections was investigated." (PMID 37318849, 2023). "Mutations in the cystic fibrosis transmembrane conductance regulator (CFTR) leads to multi-organ disease, with progressive lung disease representing the leading cause of premature death." (PMID 38075070, 2023). "CFTR encodes for an epithelial chloride channel, and although CF affects multiple organ systems it is the progressive lung disease that is the major cause of mortality and morbidity." (PMID 37165031, 2023). "Gene-addition therapy offers the potential of a curative universal treatment for CF lung disease by using a vector to deliver wild-type CFTR to the relevant airway cells to correct the underlying genetic defect for all CF mutations." (PMID 37165031, 2023). "Pancreatic sufficiency and milder lung disease are associated with lower sweat chloride levels, as was seen in the obese group, likely due to relatively increased CFTR function and subsequently less severe disease." (PMID 36320654, 2022). "In spite of significant advances in treatment procedures focusing on CFTR potentiator drugs, respiratory infections remain an important cause of lung disease." (PMID 36593975, 2022). "TCT with ETI significantly improved pulmonary function and CFQ-R respiratory domain over 48 weeks in 26 pwCF homozygous for the F508del CFTR mutation and advanced lung disease." (PMID 35207295, 2022). "Current evidence suggests that CFTR modulators are unable to eradicate pathogenic organisms in those with already established lung disease." (PMID 35408875, 2022).
lung disease (continued). "Whilst prevalent CFTR mutations are an important determinator for the severity of CF lung disease, the genotype–phenotype correlation between the genetically determined loss of CFTR function and lung function decline is approximately 60%." (PMID 35525938, 2022). "While the current gene therapy development efforts target life-threatening lung disease via CFTR replacement (gene addition) or mutation repair (gene editing), it is worth mentioning that Cl− secretion in airway epithelial cells is not limited to CFTR." (PMID 36304167, 2022). "CFTR dysfunction leads to many manifestations in the organs where it is expressed but the lung disease remains the leading cause of morbidity and mortality (responsible for the mortality of 66.14% of CF patients in Europe in 2018)." (PMID 34944110, 2021). "Among the multifunctional defects associated with defective CFTR, increasing evidence supports the relevant role of perturbed calcium (Ca2+) signaling in the pathophysiology of CF lung disease." (PMID 33776759, 2021). "CF lung disease is characterized by abnormal chloride transportation and profound inflammatory phenotype, due to mutations in the CFTR gene, the most frequent being deletion of F508." (PMID 34404863, 2021). "CF pigs engineered by mutating CFTR develop lung disease that mimics human CF, and are well-suited for investigating CF lung disease therapeutics." (PMID 33923029, 2021). "The variant L997F was initially considered as a polymorphism and was subsequently reported to cause CFTR-RDs, such as lung diseases, disseminated bronchiectasis, idiopathic pancreatitis, CBAVD, and neonatal hypertrypsinemia with normal sweat test." (PMID 33613790, 2021). "We propose that CFTR deficiency causes oxidative stress in CF airway epithelium, affecting multiple bioactive lipid metabolic pathways, which likely play a role in CF lung disease progression." (PMID 33613309, 2021). "The rare Cystic Fibrosis Transmembrane Conductance Regulator (CFTR) mutations, c.1826A > G (H609R) and c.3067_3072delATAGTG (I1023_V1024del), are associated with severe lung disease." (PMID 33920764, 2021). "CF affects multiple organs and despite symptomatic treatments and CFTR modulator therapies that improve quality of life it remains incurable, with lung disease the major cause of mortality." (PMID 34084147, 2021). "Traditionally, in vitro study of CF lung disease has focused on the study of airway epithelial cells carrying CFTR mutations." (PMID 32492951, 2020). "Our results describe a unique examination of the dynamic of the lung microbiome in patients with moderate-severe lung disease carrying the ΔF508 mutation of CFTR gene and containing clinical measurements over a 15-month period." (PMID 32635564, 2020). "Transforming growth factor (TGF)-β1 is a well-established gene modifier of CF associated with worse lung disease in F508del-homozygous patients, by inhibiting CFTR biogenesis and blocking the functional rescue of F508del-CFTR." (PMID 32117984, 2020). "At any rate, the pathogenic concept of airway acidification as the initiator of CF lung disease is also seriously questioned by the recent findings that patients with a loss of TMEM16A-function also lack CFTR function." (PMID 32712714, 2020). "A pathogenic concept was established in which CF lung disease starts with reduced HCO3− secretion caused by impaired CFTR function." (PMID 32712714, 2020). "Although the role of CFTR in transepithelial ion transport is widely accepted, the exact mechanisms underlying CF lung disease development have long been debated." (PMID 29609604, 2018). "In contrast to tobacco-induced acquired CFTR deficiency, mucus hypersecretion in CF lung disease develops secondary to inflammatory response." (PMID 29896115, 2018). "Lung disease progression is variable among CF patients and depends on the combination of three factors: (i) DNA mutations in the CFTR gene, (ii) polymorphic variations in other genes, and (iii) environmental exposure." (PMID 28289476, 2017).
lung disease (continued). "At a lower infection dose, we also observed CFTR-related susceptibility to lung disease with virulent highly encapsulated pneumococci measured by bacterial load in BAL fluids and lung tissue at 5 days and 24 hours post-infection." (PMID 26469863, 2015). "Overall, these results suggest a potential benefit of ivacaftor in patients with the Arg117His CFTR mutation and more advanced lung disease." (PMID 26403534, 2015). "Pancreatic sufficiency (PS) is associated with CFTR mutations that retain residual activity and is characterized by milder, less progressive lung disease." (PMID 25822311, 2015). "Other conditions frequently observed in patients affected by NTM pulmonary disease are scoliosis, pectus excavatum, mitral valve prolapse, and cystic fibrosis transmembrane conductance regulator (CFTR) mutations." (PMID 26106603, 2015). "Not surprisingly, multi-dimensional clinical phenotyping identified classes with milder lung disease, PS and a higher frequency of CFTR Class IV, V, and VI mutations." (PMID 25822311, 2015). "We describe the first use of ß-adrenergic sweat secretion to detect CFTR dysfunction in individuals with smoking-related lung disease providing strong evidence that COPD is associated with acquired CFTR dysfunction in extra-pulmonary organs." (PMID 24568560, 2014). "Here, we investigated apical CFTR localization of nasal epithelial cells obtained from subjects with CF and healthy controls, and assessed associations with lung disease." (PMID 23483918, 2013). "Further, we crossed βENaC-Tg mice with CFTR-deficient mice to validate the role of CFTR in early lung disease." (PMID 22937152, 2012). "One case report describes two CF patients with a nonsense mutation in CFTR and mild pulmonary disease." (PMID 20420703, 2010). "Since these patients generally had a sufficient level of pancreatic function, it was concluded that CFTR genotypes associated with long-term pancreatic sufficiency have more benign lung disease and better pulmonary function." (PMID 19909502, 2009). "Mutations in CFTR cause CF, and the initial pathophysiology of the lung disease involves defective ion transport, dehydration of the mucous layer, and reduced mucociliary and cough clearance." (PMID 19169360, 2009). "Because CFTR modulators act systemically, and a lung-directed gene therapy would only ameliorate the lung disease, patients with appropriate variants may want to continue with modulator therapy to manage systemic symptoms." (PMID 39439894, 2024). "CFTR dysfunction causes impaired mucociliary clearance, leading to chronic airway infections, and a vicious cycle of lung inflammation and damage, resulting in progressive lung disease, the major cause of morbidity and mortality in CF patients." (PMID 37052589, 2023). "This study adds to the growing literature suggesting that the effects of heterozygous CFTR mutations on circulating monocytes could increase the prevalence of infection, ultimately leading to chronic bronchitis and severe lung disease." (PMID 35315363, 2022). "However, both intrinsic and extrinsic variables directly and/or indirectly associated with CFTR likely influence the course of CF, particularly the immune/inflammatory phenotype of CF lung disease." (PMID 35315363, 2022). "The mechanisms behind the pathophysiology seen in the lungs of the CVB1-infected F508del mice could be investigated in future studies with an aim to understand how mutations in CFTR heighten the risk of pulmonary disease." (PMID 36157581, 2022). "Taken together, the present data question the pathogenic role of defective CFTR-dependent ion transport and acidic pH in CF, but rather suggest that intrinsic airway inflammation along with Na+ hyperabsorption is the cause for CF lung disease." (PMID 32712714, 2020).
lung disease (continued). "Two phase 3 randomized clinical trials (TRAFFIC and TRANSPORT) investigated the comparative safety and efficacy of Orkambi® in patients with CF who were 12 years old and older with mild to moderate lung disease and who were homozygous for the F508del-CFTR mutation." (PMID 32244302, 2020). "However, after the identification and cloning of the gene encoding the CFTR in 1989, along with an increased knowledge on how CFTR dysfunction causes lung disease, new targets and approaches for the CF treatment have been investigated." (PMID 31921811, 2019). "In the present study, the distribution for F508del CFTR mutation proportions is similar between the two cohorts but it is now well established that other mutations are associated, for some of them, with lung disease severity and for others, with diabetes susceptibility." (PMID 30894563, 2019). "Given that CS is a major cause of lung disease and that loss of CFTR expression induced by CS is Ca2+-dependent, our data may help in the development of new strategies to minimise the deleterious effect of CS on CFTR function." (PMID 30547226, 2019). "Because individuals with identical CFTR mutations may differ in their pulmonary disease, it has been postulated that other genetic factors (i.e. gene modifiers) as well as the microenvironment may contribute to the variable outcome of pulmonary disease." (PMID 30333828, 2018). "Assuming a patient has the right CFTR mutation class, these personalized medicines can increase the presence and/or function of the CFTR protein in the cell, improve lung function, and slow lung disease progression." (PMID 30538635, 2018). "We sought to address whether CF macrophages have a primary functional defect as a consequence of CFTR loss and thus contribute to the onset of infection and inflammation observed in CF lung disease." (PMID 28377087, 2017). "Future studies thus need to characterize the involved GR isoforms and determine whether a short-term GC exposure yielding to rapid increases of CFTR activity harbors a risk for GC-resistant lung disease." (PMID 28825630, 2017). "However, the sequence of events that result in lung disease from cystic fibrosis transmembrane conductance regulator (CFTR) mutations is not fully understood." (PMID 28983075, 2017). "Given the importance and the renewed interest in neutrophils as instrumental actors in immune deregulation associated with lung disease in CF, promoting CFTR-dependent antimicrobial function or targeting neutrophils to promote their apoptosis is a timely issue that should be addressed." (PMID 28713772, 2017). "The advent of the CF pig has facilitated advancements in our understanding of CF lung disease as, like man, it develops a spontaneous lung disease phenotype with spontaneous bacterial colonization and associated innate immune dysfunction when CFTR function is lost." (PMID 27025615, 2015). "Overall, this gene-based (CFTR) statistic showed that CFTR and lung disease severity are associated (P=0.0043, from a permutation-based test that is then meta-combined using Stouffer's Z-score method), but the evidence is very modest compared to the evidence for multiple modifier loci reported here." (PMID 26417704, 2015). "Furthermore, ferrets with loss of CFTR function also develop lung disease with similarities to the human disease." (PMID 27025615, 2015). "Our studies have revealed a CFTR-related susceptibility to lung disease with virulent highly encapsulated pneumococci as measured by survival at 5 days, bacterial load in BAL fluids and lung tissue, and time to moribund state followed by infections with 7 x 105 CFU." (PMID 26469863, 2015). "Differences in apical CFTR expression between patients may be used to tailor personalized medicine approaches for CFTR-restoring drugs in the future, and may select individuals that are at increased risk to develop lung disease." (PMID 23483918, 2013).
lung disease (continued). "These modifier genes could indirectly affect CF lung disease as has been shown for e.g. polymorphisms in the TGFβ1 gene, but could also directly affect mutant CFTR protein function." (PMID 23483918, 2013). "Mutations in the cystic fibrosis transmembrane regulator (CFTR) lead to death from lung disease." (PMID 24378849, 2013). "The robust response of MCT to the application of the CFTR potentiator ivacaftor, an agent with a high degree of selectivity for CFTR, further strengthens the argument that deficient CFTR activity has an important role governing delayed MCC in smoking-related lung diseases." (PMID 22768130, 2012). "Several hypotheses link mutations in CFTR to development of lung disease in CF, whose hallmarks are bacterial infection with opportunistic pathogens and a vicious neutrophil-dominated chronic inflammatory response." (PMID 21994643, 2010). "Furthermore, we show that the association between CFTR genotype and respiratory infection has a complex relationship with the severity of lung disease." (PMID 20932301, 2010). "Thus, loss of CFTR function in macrophages influences cell homeostasis, leading to a dysregulated cellular response to infection that may exacerbate CF lung disease." (PMID 38035088, 2023). "Dysfunctional CFTR leads to the over-accumulation of dehydrated mucus in the lung, which impairs the ability of the lung to expel inhaled pathogens, causing chronic infection, inflammation, and fibrosis, and leading to early death due to progressive lung disease." (PMID 34615919, 2021). "The concept that inadequate hydration of the airway mucosa drives CF lung disease throughout life is likely an oversimplification, as additional factors such as loss of alkalinisation of the mucosa through impaired CFTR-mediated bicarbonate secretion may also contribute to the disease phenotype." (PMID 32235608, 2020). "In addition to the environmental impact of CFTR mutations there is also variability between CF patients, despite identical CFTR genotypes, indicating that other genetic factors contribute to the severity of lung disease." (PMID 33291484, 2020). "Additionally, although patients with CFTR c.3718-2477 C>T mutations have mild phenotypes outside of lung disease, systemic delivery of ASOs may also be considered to correct CFTR expression in additional tissue types." (PMID 32520327, 2020). "We need to investigate the impact of novel CFTR modulating agents on the lung microbiome, and we need to improve and harmonize prophylactic- and treatment strategies for high risk populations (e.g., end stage CF lung disease and CF patients after lung transplantation)." (PMID 33371198, 2020). "Also interesting for the discussion is the hypothesis that even a single mutation in CFTR gene may contribute to the development of lung disease." (PMID 30151190, 2018). "In addition, variants in the CFTR gene may cause several clinical phenotypes, such as chronic sinusitis, gastrointestinal disorders, and pulmonary diseases." (PMID 29124052, 2017). "CFTR gene is located at the chr7q31.2 and a genome-wide association analysis identified five loci that display significant relevance in the variable manifestation and progression of lung disease in CF (chr3q29, chr5p15.3, chr6p21.3, chr11p12-p13 and chrXq22-q23)." (PMID 27656143, 2016). "Although the significance of these findings at the functional level requires further investigation, a defective ENaC protein may be involved in some patients with idiopathic bronchiectasis or cystic fibrosis-like lung disease with only one CFTR mutation identified." (PMID 18507830, 2008). "More than 1,200 variants of the cystic fibrosis transmembrane conductance regulator gene (CFTR) are associated with cystic fibrosis, an autosomal recessive pulmonary disease affecting over 100,000 people." (PMID 42282787, 2026). "Traditionally, the care of CF lung disease has involved multiple measures to address the consequences of CFTR dysfunction." (PMID 40144821, 2025).